S100A9 (S100 calcium binding protein A9)
Diseases named in the same sentence as S100A9 in open-access papers (continued):
Sharing a sentence is not in itself a finding about the gene and the disease.
chronic obstructive pulmonary disease (10 papers, 2015 to 2025). A chronic and progressive lung disorder characterized by the loss of elasticity of the bronchial tree and the air sacs, destruction of the air sacs wall, thickening of the bronchial wall, and mucous accumulation in the bronchial tree. "Very recently, the surface expression of CD163 and S100A9 on classical monocytes has been associated with chronic obstructive pulmonary disease (COPD) and host background factors, such as age and smoking." (PMID 34108546, 2021). "During respiratory syncytial viral-induced exacerbation of chronic obstructive pulmonary disease, PTPN1 deficiency was shown to promote disease symptoms partly through enhancing S100A9 levels, a damage-associated molecular pattern molecule." (PMID 36672250, 2023). "A microRNA-21-mediated SATB1/S100A9/NF-κB axis has been reported to promote chronic obstructive pulmonary disease pathogenesis." (PMID 35935235, 2022). "In addition, airway inflammation induced by the S100A9/nuclear factor-κB signaling cascade was the key mechanism responsible for smoking-related chronic obstructive pulmonary disease." (PMID 36977670, 2023). "S100A9 does not appear to increase in patients with an infectious flare up of chronic obstructive pulmonary disease (COPD), despite the fact that increased expression of S100 proteins has been linked to disease exacerbation." (PMID 34063831, 2021). "Although the excessive expression of S100 proteins reveals a strong connection with exacerbation of disease, none of S100A9 is observed increasing in patients with unstable chronic obstructive pulmonary disease (COPD) resulted from infection." (PMID 29942307, 2018).
Insulin resistance (10 papers, 2019 to 2025). Increased resistance towards insulin, that is, diminished effectiveness of insulin in reducing blood glucose levels. "Gal-3 and S100A9 levels were measured and correlated with clinical parameters, including glucose metabolism and insulin resistance." (PMID 37915694, 2023). "Further analysis showed that Gal-3 and S100A9 were involved in promoting insulin resistance." (PMID 37915694, 2023). "Additionally, serum levels of S100A4, S100A8/S100A9, S100A12, and S100B correlate with insulin resistance/T2D, metabolic risk score, and fat cell size." (PMID 35328627, 2022). "We previously discovered that PC-derived S100A9 could induce insulin resistance by inhibiting insulin-stimulated glucose uptake in muscle cells and thereby led to PCDM, a paraneoplastic phenomenon occurring in approximately 50% of PC patients within 24 months before the diagnosis of cancer." (PMID 37280516, 2023).
liver cancer (10 papers, 2015 to 2025). An epithelial or non-epithelial malignant neoplasm that arises from the liver. "Most S100 family members, such as S100A8 and S100A9, have already been reported to be involved in liver cancer." (PMID 40352930, 2025). "Previous studies have reported a significant increase in the expression of S100A9 in the tissues and serum of liver cancer patients." (PMID 37405532, 2024). "The upregulation of S100A8 and S100A9 correlates with poor differentiation of human liver cancer cells and tissues." (PMID 34517344, 2021). "Our present study indicated that HBx promoted HCC cell growth and metastasis both in vitro and in vivo, which was partially mediated by enhanced expression of S100A9 from liver cancer cell expressing HBx." (PMID 29795379, 2018). "The risk model for liver cancer patients includes NQO1, NT5DC2, and S100A9 as risk genes." (PMID 37405532, 2024). "Although S100A9 was overexpressed in liver cancer cells, it is also intensely upregulated in myeloid cells under pathological conditions, which may account for its higher expression levels in adjacent normal tissues." (PMID 35560794, 2022). "To date, studies on S100A9 and PPARGC1A have been suggested as a new potential biomarker for liver cancer." (PMID 36120553, 2022). "Members of the S100 calcium binding protein family, namely, S100A7, S100A8, S100A9, and S100A10, exert a momentous function in tumor growth and metastasis, such as breast and liver cancer." (PMID 36421685, 2022). "In our results, S100A9, SLC22A15, TRIM54, and PPARGC1A were identified as TIMGs, which were identified as prognostic biomarkers for liver cancer sufferers." (PMID 36120553, 2022). "On the other hand, CHI3L1 may negatively regulate S100A9 and S100A4, which means that its interaction with S100A9 and S100A4 results in a reduction in the proinflammatory effects of S100A9 and S100A4 in liver cancer." (PMID 38177294, 2024). "Overall, S100A9, SLC22A15, TRIM54, and PPARGC1A were screened as TIMGs that can be used for prognostic prediction and be the potential targets of the ICI treatments for patients with liver cancer." (PMID 36120553, 2022).
ulcerative colitis (10 papers, 2012 to 2025). An inflammatory bowel disease involving the mucosal surface of the large intestine and rectum. "CXCR2 and S100A9 are neutrophil-related biomarkers and potential therapeutic targets in ulcerative colitis." (PMID 38034382, 2023). "Circulating levels of S100A9 also correlate strongly with the histological score of disease severity of ulcerative colitis." (PMID 36364715, 2022). "Notably, S100A9 has emerged as a promising biomarker for the early diagnosis of ulcerative colitis, particularly in pediatric and adolescent patients with UC." (PMID 40565156, 2025). "Measurement of S100A8/S100A9 in feces is considered a reliable method to distinguish IBD patients from those without chronic intestinal inflammation and it is, together with serum levels of S100A8/S100A9, useful in monitoring inflammation in patients with Crohn’s disease or ulcerative colitis." (PMID 37372165, 2023). "On the other hand, S100A8, S100A9, S100A10, and S100A4 displayed heterogeneous expression patterns in ulcerative colitis patients showing neoplasia." (PMID 23166536, 2012). "S100A9 is best known as a dimerization partner of S100A8, forming calprotectin, which is used as an effective marker of gut inflammation in patients with Crohn’s disease and ulcerative colitis." (PMID 34884728, 2021).
acute lymphoblastic leukemia (9 papers, 2017 to 2024). Leukemia with an acute onset, characterized by the presence of lymphoblasts in the bone marrow and the peripheral blood. "Elevated expression of S100A8/S100A9 caused glucocorticoid resistance in MLL rearranged infant acute lymphoid leukemia and negatively associated with BCL2 inhibitor venetoclax in AML." (PMID 34485305, 2021). "In addition, elevated S100A8 and S100A9 cause glucocorticoid resistance in pediatric acute lymphoblastic leukemia." (PMID 29955397, 2018). "In AML2 and AML3, the upregulated genes contained S100A8 and S100A9, which are known to be poor prognostic indicators in AML, and elevated expression of the heterodimer S100A8/S100A9 was previously reported to cause glucocorticoid resistance in MLL-rearranged infant acute lymphoid leukaemia cells." (PMID 37615858, 2024). "We also found that ARG1 gene expression was restricted to the single erythroid cell cluster that we termed ARG1-positive Orthochromatic erythroblasts and that late Erythroid cells lose S100A9 and gain MZB1 gene expression in case of acute lymphoblastic leukemia." (PMID 39267736, 2024). "Deregulations of the expression of the S100A8 and S100A9 genes and/or proteins, as well as changes in their plasma levels or their levels of secretion in the bone marrow microenvironment, are frequently observed in acute myeloblastic leukemias (AML) and acute lymphoblastic leukemias (ALL)." (PMID 33801279, 2021). "In pediatric acute lymphoblastic leukemia (ALL), as expected, since normal lymphoid cells do not express S100A8 and S100A9, the expression levels of these genes were significantly lower than in AML." (PMID 33801279, 2021).
breast tumor (9 papers, 2015 to 2024). "Overexpression of S100A9 inhibited antitumoral immunological activity in the tumor microenvironment via promoting tumor cell metabolism in HER2 positive breast tumors." (PMID 39830522, 2024). "Histology analysis of the resected breast tumors before treatment and the small nodules detected after treatment and detected reduced protein levels of S100a9 and Cxcl12." (PMID 35304461, 2022). "Aiming at further characterizing the significance of S100A8 and S100A9 in breast malignancy, we defined their expression pattern among the different breast tumor subclasses." (PMID 35655319, 2022). "In support of these observations, S100A9 also contributes to H-ras-mediated human breast epithelial cell migration and invasion and to the recurrence of breast tumors with chromosome 1q21.3 amplification." (PMID 35484101, 2022). "The mRNA levels of S100A8 were significantly lower but that of S100A9 was significantly higher in ER+-breast tumor than in ER--breast tumor." (PMID 29416786, 2018). "While mRNA encoding the myeloid cell marker CD11b (ITGAM) was expressed at equal levels in all breast tumour subgroups, mRNA of the anti-inflammatory markers CD163 and S100A9 were expressed at significantly higher levels in basal than luminal A breast tumours." (PMID 27725631, 2016). "Ghavami and colleagues demonstrated that S100A8/S100A9 proteins used at a concentration of 10 μg/mL induced growth of several breast tumor cell lines including MCF-7, MDA-MB231, and SHEP, whereas at higher concentrations it did not enhance cellular proliferation." (PMID 36923707, 2023). "Moreover, the expression of S100A9 was found significantly down-regulated in BC metastatic samples respect to breast tumor samples." (PMID 35655319, 2022). "S100A8 overexpression in high-grade breast tumors in comparison to low-grade tumors has been previously reported and associated with poor prognosis, poor tumor differentiation, LVI, and node metastasis when co-expressed with S100A9." (PMID 25391423, 2015). "We also found that there were increased Pdl1 and Pd1 staining in breast tumor tissues from Brca1Co/Co;MMTV-Cre treated either with Tas for S100A9 or AMD3465 which is an inhibitor for CXCR4, a receptor for CXCL12." (PMID 35304461, 2022). "Of note, our bioinformatics investigation has revealed that S100A8 and S100A9 are greatly expressed in breast tumor tissues rather than in its normal counterpart." (PMID 35655319, 2022). "In this study, we demonstrate that co-transplanted primary human monocytes differentiate into CD163+ myeloid cells, both in luminal A and TN breast tumour grafts, but that the immunosuppressive MDSC-marker S100A9 (refs 37, 38) was expressed only by the CD163+ cells in the TN grafts." (PMID 27725631, 2016). "In addition, we found increased levels of S100A8 and S100A9 in TNBC and HER2-positive BC subtypes compared to Luminal-A and Luminal-B breast tumor subgroups, respectively, and we also highlight a strong correlation between S100A8 and S100A9 gene expression levels in TNBC." (PMID 35655319, 2022).
Crohn disease (9 papers, 2015 to 2025). A gastrointestinal disorder characterized by chronic inflammation involving all layers of the intestinal wall, noncaseating granulomas affecting the intestinal wall and regional lymph nodes, and transmural fibrosis. "For example, in the treatment of femoral head osteoarthritis, it reduces serum levels of S100A9 protein, thus contributing to improved tissue vascularisation, while in Crohn’s disease, it has a down-regulating effect on S100A8/S100A9 heterotetramers (calprotectin)." (PMID 40243713, 2025). "This bioinformatic study elucidates S100A8, S100A9, S100A12 and CXCR2 as hub genes for the co-occurrence of Crohn’s disease and peripheral artery disease." (PMID 35795659, 2022).
juvenile idiopathic arthritis (9 papers, 2011 to 2025). Juvenile idiopathic arthritis (JIA) is the term used to describe a group of inflammatory articular disorders of unknown cause that begin before the age of 16 and last over 6 weeks. "Higher expression of S100A8, but lower expression of S100A9 were found in tears from children with juvenile idiopathic arthritis associated uveitis (JIA-U) compared to those from idiopathic chronic anterior uveitis (I-CAU)." (PMID 38982370, 2024). "A recent study analyzed the relationship between serum S100A8/S100A9 and S100A12 and the maintenance of clinical inactive disease (CID) in patients with polyarticular forms of juvenile idiopathic arthritis (PF-JIA) while on anti-TNF- therapy and disease flare following withdrawal of treatment." (PMID 30828327, 2019).
lung diseases (9 papers, 2006 to 2025). "The clinical significance of utilizing neutralizing antibody is obvious from possible passive immunization with S100A9 antibody as a new therapeutic strategy to control lung inflammation and associated lung disease during IAV infection." (PMID 24391503, 2014). "Studies revealed that serum S100A9 levels are significantly increased in tuberculosis than in other lung diseases, suggesting that S100A9 may be a potential diagnostic biomarker for pulmonary tuberculosis." (PMID 33567747, 2021). "The precise mechanisms underlying S100A9's function within the ECM and its specific role in pulmonary diseases are subjects of ongoing investigation." (PMID 40487749, 2025). "In pulmonary diseases, active roles of S100A9 include fibroblast proliferation and collagen production upregulation." (PMID 37936894, 2023). "As a consequence, S100A9/TLR4 activity exacerbates lung disease by promoting a pro-inflammatory response and inducing cell-death." (PMID 24391503, 2014). "In various lung diseases, the S100a8/S100a9 complex exacerbates inflammatory responses by activating multiple cell surface receptors and intracellular signaling pathways (including MAPK and NF-κB), thereby promoting the emission of inflammatory mediators and the recruitment of immune cells." (PMID 41044788, 2025). "From our analyses and previous literatures, we focused on Lcn2, S100a9 and S100a8 as potential genes that may play a key role in indium-induced lung diseases." (PMID 39516272, 2025). "Since extracellular S100A9 acted as a positive regulator of pro-inflammatory response and induced apoptosis, we hypothesized that extracellular S100A9 exacerbates IAV-associated lung disease." (PMID 24391503, 2014). "Moreover, since similar elevations of S100A8/S100A9 are detected in CF patients, these results also provide justification for the application of congenic C57BL/6J CF mice as a potential model to gain insight into the pathogenesis of lung disease of CF patients and potential therapeutic avenues." (PMID 16571124, 2006).
non-small cell lung carcinoma (9 papers, 2013 to 2023). A group of at least three distinct histological types of lung cancer, including non-small cell squamous cell carcinoma, adenocarcinoma, and large cell carcinoma. "The expression of S100A9 is associated with a poor prognosis among non-small-cell lung cancer patients, which is consistent with our findings." (PMID 34374812, 2022). "Consistent with our results, previous studies showed that S100A9+ cell density was associated with a poor prognosis in patients with other cancers, such as clear cell renal cell carcinoma, invasive ductal carcinoma of the breast, and non-small cell lung cancer." (PMID 34157683, 2021). "It has been supported that early-stage non-small cell lung cancer (NSCLC) patients who had overexpression of S100A9 evaluated by immunohistochemical staining within the cancer cells, exhibited a significantly worse overall five-year survival." (PMID 33567747, 2021). "More recently, it has been reported that the suppressive activity of human MDSCs resides in a CD14+S100A9+ inflammatory monocytes in non-small cell lung cancer (NSCLC) patients 25]." (PMID 23437326, 2013). "Similarly, S100A9(+) inflammatory monocytes in patients with non-small cell lung cancer (NSCLC) are shown to suppress T-cells by production of arginase, iNOS, and the IL-13/IL-4Rα axis." (PMID 33919732, 2021).
ovarian carcinoma (9 papers, 2013 to 2025). A malignant neoplasm originating from the surface ovarian epithelium. "Overall, these results indicated that HDC downregulation induced by stress hormones promoted the proliferation, migration, and invasion of ovarian cancer cells through activation of the IL-6/STAT3/S100A9 signaling pathway." (PMID 39720595, 2024). "Specifically, chronic stress elevates stress hormone levels, stimulates relative receptors, and subsequently decreases HDC expression, promoting ovarian cancer progression via the IL-6/STAT3/S100A9 pathway." (PMID 39720595, 2024). "Chronic stress leads to the downregulation of HDC expression, thereby facilitating the progression of ovarian cancer through the IL-6/STAT3/S100A9 pathway." (PMID 39720595, 2024). "Until now, little was known about the relationship between the S100A8/S100A9 and prognosis in ovarian cancer." (PMID 30558666, 2018). "Our results showed that S100a8 and S100a9 are highly expressed in the TME of aged animals with ovarian cancer and may contribute to a more aggressive cancer phenotype in these animals." (PMID 39796176, 2025). "High expression of S100a8 and S100a9 has been reported in ovarian cancer." (PMID 39796176, 2025). "Functional investigations indicate ovarian cancer progression via the IL-6/STAT3/S100A9 pathway." (PMID 39720595, 2024). "This study aimed to investigate the impact of chronic stress on HDC expression in ovarian cancer progression and the effect of HIS on the IL-6/STAT3/S100A9 pathway." (PMID 39720595, 2024). "S100A8 and S100A9, also known as Calgranulins A and B, were first identified in cyst fluid and serum as up regulated in ovarian cancer, but absent or negative in benign cysts." (PMID 23557354, 2013). "S100A8 and S100A9 are involved in numerous inflammation and carcinogenesis cellular processes and can be used as cancer biomarkers, but are not specific markers for ovarian cancer." (PMID 23557354, 2013). "However, higher expression of S100A9 was not correlated with prognostic value in ovarian cancer patients." (PMID 30558666, 2018). "The downregulation of HDC expression led to the activation of the IL-6/STAT3/S100A9 pathway, stimulating Th17 cells to secrete IL-17A, thereby promoting ovarian cancer progression, which suggests that HDC may be a potential therapeutic target for the comorbidity of ovarian cancer and depression." (PMID 39720595, 2024).
pneumonia (9 papers, 2012 to 2025). An acute, acute and chronic, or chronic inflammation focally or diffusely affecting the lung parenchyma, caused by an infection in one or both of the lungs (by bacteria, viruses, fungi, or mycoplasma.). "Since S100A9 KO mice also succumbed to neutrophil-dominated severe pneumonia, we next examined release of neutrophil elastase in BALF supernatant of S. pneumoniae-infected WT as compared to S100A9 KO mice." (PMID 37467233, 2023). "Particularly in S100A9−/−, and to a lesser extent in TLR4PF4Cre+ mice, cytokine levels were strongly increased during pneumonia compared to WT controls." (PMID 36497202, 2022). "Similarly, WT bone marrow reconstitution in S100A9 KO mice rescued mice from fatal pneumonia (survival at 90%), while > 80% KO→KO mice succumbed to pneumococcal pneumonia." (PMID 37467233, 2023). "Also, neutrophils purified from S100A9 KO and WT mice responded with a similar respiratory burst induction to S. pneumoniae-infection in vitro." (PMID 37467233, 2023). "The levels and changes of S100A9 in patients with other pneumonias are unclear." (PMID 33827454, 2021). "Messenger RNA (mRNA) sequencing from the peripheral blood of patients with pneumonia revealed that S100A9 might contribute solely to mild pneumonia." (PMID 33567747, 2021). "The difference of S100A9 will be compared between CAP patients and other pneumonias’ patients in the next work." (PMID 33827454, 2021).